SHANK3 (SH3 and multiple ankyrin repeat domains 3)
Diseases named in the same sentence as SHANK3 in open-access papers (continued):
Sharing a sentence is not in itself a finding about the gene and the disease.
autism (continued). "In mice, sevoflurane exposure induced autism-like behaviours and led to the downregulation of high-risk autism genes, including ARID1B, GABRA5, GABRB3, GRIN2B, SHANK3 and SUV420H1." (PMID 39372140, 2024). "Shank3 haploinsufficiency causes morphological and functional abnormalities in PFC pyramidal neurons, supporting the notion that Shank3 mutant dogs are new and valid animal models for autism research." (PMID 38297387, 2024). "For example, repetitive behavior deficits, as one of the core symptoms of autism, are frequently reported in ASD patients, including those with Shank3 mutations." (PMID 38900384, 2024). "Shank3-altered mice and children with autism often have eating disorders, and the center of feeding regulation is hypothalamus." (PMID 38570876, 2024). "Shank3 mutant dogs exhibit autism-like social deficits, including social withdrawal, elevated anxiety, and greater sensitivity to deviant tones." (PMID 38297387, 2024). "Our results unveil that p38α signaling in AgRP neurons plays a critical role in the development of autism, particularly in the SHANK3 pathway mutant-related population." (PMID 38570876, 2024). "Many genes are associated with autism spectrum disorders, and copy number variations and rare gene mutations (e.g., SHANK3, NRXN1, CHD8, SCN2A) are closely linked to autism." (PMID 39734494, 2024). "The complex nature of the E/I imbalance phenotypes and autistic-like behaviours found in each of these studies suggests that the contribution of Shank3 to E/I imbalance in autism is sub-region and likely cell-type specific." (PMID 37441676, 2023). "A translational study using proton magnetic resonance spectroscopy ([1H]MRS) in humans and six diverse autism rodent models, including Shank3, reported glutamatergic and GABAergic genetic links to autism traits." (PMID 37441676, 2023). "Very recently, 7-NI was also used to demonstrate the pathological role of NO in autism development, and the in vivo administration of this compound to a Shank3 mouse (M1) model of autism disease led to the recovery of a normal behavioral phenotype." (PMID 37764469, 2023). "Reduced villi length has also been reported in Shank3 Knockout mice (which is a genetic model of autism)." (PMID 37316481, 2023). "Multiple studies in both preclinical studies of iPSC-neurons and rodent models of autism have shown hyperexcitability, strongly implicating Shank3 in E/I imbalance and indicating the potential for successful cross-species phenotyping." (PMID 37441676, 2023). "Combined, these studies indicate that the contribution of Shank3 to the E/I imbalance in autism stems from its role as a scaffold for AMPA/NMDA receptors at synapses." (PMID 37441676, 2023). "For example, we observed a decrease of Grm2, encoding mGluR2, a G-protein-coupled glutamate receptor which interacts with the proline-rich domain of SHANK3 and which has been found decreased in a valproate-induced rat model of autism." (PMID 37008785, 2023). "Behaviourally, Nrxn1 and Shank3 animal models display autism-related behaviours that are consistent with observations in clinical studies." (PMID 37441676, 2023). "Increased maternal dietary zinc during pregnancy and lactation alters Shank3-/--induced autism-like behaviors, possibly related to postsynaptic NMDA receptor-mediated currents and altered glutamatergic presynaptic function." (PMID 36602746, 2023). "More evidence of the importance of histone acetylation in regulating glutamate receptor expression can be further acquired from the previous findings in substance abuse models and in a Shank3 mouse model of autism." (PMID 37438762, 2023). "The presence of repetitive behaviours, a core feature of autism and PMD, is the most robust phenotype observed in the Shank3-KO murine models of autism." (PMID 37441676, 2023). "Kim and colleagues suggested a central role for the cortico-basal ganglia-thalamic circuits in repetitive behavior in autism mouse models and also discussed the role of SHANK3." (PMID 36699652, 2022).
autism (continued). "In humans, mutations in Shank3 may result in Phelan-McDermid syndrome, which is characterized by developmental delay, absent or delayed speech, hypotonia, intellectual disability, and in most of the cases, the core symptoms of autism (repetitive behavior, social and communication deficits)." (PMID 35884680, 2022). "This study investigated the developmental aspect of autism-related behaviors and other phenotypes in a Shank3-transgenic mouse model." (PMID 36699652, 2022). "Collectively, our data highlight the NAc Trpv4 alterations as a potentially common and unifying molecular underlying factor in sociability and aberrant intrinsic neuronal properties in Shank3 mouse models for autism." (PMID 35022531, 2022). "Our research presents a profound investigation of the influences of chronic treatment with medical cannabis oil in the InsG3680 Shank3 mutant mouse model of autism." (PMID 34645786, 2021). "This is consistent with several previously published mouse models related to autism, including Chd8+/−, 22q11.2, Fmr1, Itgb3, En2, Nrxn1a, and Shank3." (PMID 33757588, 2021). "Human iPSC cells with a knockdown of SHANK3, an autism-related gene, or neurons derived from iPSC from patients with Rett syndrome also exhibited reduced soma size." (PMID 34924936, 2021). "We used an autism model with compromised glutamatergic signaling, the Shank3+/– mouse, to study the circadian rhythm architecture of locomotion behavior and its entrainment to light." (PMID 33679297, 2021). "Mutations or deletions of SHANK3 result in Phelan‐McDermid syndrome (PMS), and PMS has been associated with autism, schizophrenia, and bipolar disorder." (PMID 34188957, 2021). "Diverse findings from SHANK3 mouse models thus indicate that traits related to communication, autism, and bipolar disorder are impacted by SHANK3 gene alteration." (PMID 34188957, 2021). "In this study of Phelan McDermid syndrome, characterized by deletion of the SHANK3 gene located on 22q13.33, the authors found that out of 24 adult patients, four developed regression during early adulthood and two of these had autism." (PMID 34777033, 2021). "Mutations in the gene encoding SH3 and multiple ankyrin repeat domains 3 (SHANK3), a postsynaptic scaffolding protein, have been discovered in ASD patients, making it a prominent autism gene candidate." (PMID 34712123, 2021). "We genotyped the nonsynonymous, functional SHANK3 SNP rs9616915 in a large population of typical individuals scored for autism spectrum traits (the Autism Quotient, AQ) and schizotypy spectrum traits (the Schizotypal Personality Questionnaire, SPQ-BR)." (PMID 34188957, 2021). "High genetic variations in SHANK3 were identified in the Autism Genetic Resource Exchange sample, together with HOMER1 variants." (PMID 34627165, 2021). "For example, prolonged monitoring approaches help to uncover the interplay of genetic factors and time, like in a study of locomotor activity in four genetic mouse models for autism: Shank3−/−, Cntnap2−/−, Frm1−/−, and Pcdh10+/−." (PMID 34630052, 2021). "An alteration of NMDAR has been highlighted in several mouse models of autism such as Shank3 DC/DC mice, neuroligin-3 R451C knock-in mice, Fmr1−/− mice, and Shank2−/− mice." (PMID 32182969, 2020). "Taken together, our data indicate that intranasal treatment with MSC-exo improves the core ASD-like deficits of this mouse model of autism and therefore has the potential to treat ASD patients carrying the Shank3 mutation." (PMID 32807217, 2020). "Autism risk genes, ARID1B, SHANK3 and NRXN2 were specially of interst, using a dual-luciferase assay we confirmed the direct targeting of MRE of SHANK3 by miR-873 albeit, WT and Mut miR-873 mimics similarly dysregulate Renilla luciferase." (PMID 33262327, 2020).
autism (continued). "This study confirms that early genetic restoration of a Shank3 mutant mouse model can ameliorate behavioral symptoms with face validity for autism." (PMID 32327468, 2020). "In an ASD animal study, many genes and proteins were found to be changed, such as the autism-related susceptibility genes BDNF, Shank3, and ERK1." (PMID 33456456, 2020). "Transcriptomic analysis revealed a down-regulation of autism-related (Shank3, Auts2, Ctnnd2, Nrxn2) and glutamatergic (Grm4) genes in aggressivemice." (PMID 33659799, 2020). "In the reference genome, there is a non-canonical splice acceptor at the 3′ end of the intronic sequence between exons 11 and 12 of SHANK3, a prominent candidate gene for autism, schizophrenia, Phelan-McDermid syndrome, and other disorders." (PMID 33127893, 2020). "In the current study, a dual-luciferase reporter assay confirmed miR-873 variants have a 20-30% inhibition/dysregulation effect on candidate autism risk genes ARID1B, SHANK3 and NRXN2 and also confirmed the affected expression with qPCR." (PMID 33262327, 2020). "Mei and co-workers showed that adult restoration of the SHANK3 gene selectively rescues certain synaptic defects and autism-related behaviors, such as social interaction and stereotyped and/or repetitive behavior in mice." (PMID 32521803, 2020). "Ellegood and colleagues showed in a cross-sectional study with 26 autism mouse models in 8-week-old mice that only six had an increased striatal size, including a Shank3 isoform-specific knockout at approx. the same age as our later measurement point." (PMID 30853900, 2019). "Three different autism mouse models were analyzed, namely a heterozygous and a full knockout of Shank3 isoforms (Shank3+/– and Shank3−/−), and a model of PZD." (PMID 30853900, 2019). "In the present study, we sought to answer whether autism caused by SHANK3 mutation is a “hard-wired,” irreversible neurodevelopmental disorder or a disorder of brain function that can be reversed by normalizing SHANK3 expression following completion of brain development." (PMID 31451607, 2019). "A reduced association of mGlu5 receptors with long Homer isoforms has been reported in mouse models of monogenic autism, such as Fmr1 and Shank3 knockout mice." (PMID 29615849, 2018). "This is partly due to the genetics of the patients; thus some variations found in SHANK3 in autism patients are inherited from healthy parents (e.g., R12C and R300C), ruling out a dominant effect on disease." (PMID 30131675, 2018). "Among these genes, the SHANK family is of interest since mutations in each of the three members of this family (SHANK1, PROSAP1/SHANK2, and PROSAP2/SHANK3) have been identified in patients with autism, but with a gradient of severity." (PMID 30337855, 2018). "We have recently demonstrated that the autism gene SHANK3 is expressed by both mouse and human DRG neurons and regulates TRPV1 function in the DRG neurons of both species, offering a novel peripheral mechanism of pain dysregulation in autism." (PMID 28424991, 2018). "These mice were used to interrogate the circuit/brain-region and cell-type specific role of Shank3 in the expression of autism-related behaviors." (PMID 29700290, 2018). "It was shown that re-establishing Shank3 levels after birth can ameliorate autism-like symptoms in mice." (PMID 29875651, 2018). "With the recent finding of ADNP as being one of a small group of genes, including CHD8 and SHANK3 that appear to lead to autism in a substantial proportion of cases, the significance of our current results is enhanced." (PMID 28221363, 2017).
autism (continued). "Since there is evidence that SHANK3 is involved in other forms of autism, these rats will also be useful in understanding the other ways in which autism can develop." (PMID 28139198, 2017). "For example, in a mouse Shank3 autism model, rescuing the mutant Shank3 protein in the adult was sufficient to rescue social interactions and excessive grooming but not anxiety and repetitive motor behaviors." (PMID 27458342, 2016). "Here, we examined adult neurogenesis in the hippocampus, as well as astroglia and microglia in the hippocampus, mPFC, and striatum of two models that display autism-like phenotypes, Cntnap2−/− and Shank3+/ΔC transgenic mice." (PMID 27785461, 2016). "We expect that the autism kits with the probes covering the most recurrent CNVs in autism, 15q11-q13 and 16p11 regions together with SHANK3 and SHANK2 genes, have a detection rate of about 2-6%." (PMID 28357200, 2016). "Intriguingly, re-expressing Shank3 in adulthood is sufficient to restore parts of the autism-related phenotypes in mice." (PMID 27909399, 2016). "One of the few single-locus causes of autism involves a mutation in the SH3 and multiple ankyrin repeat domains 3 (SHANK3) gene." (PMID 26137200, 2015). "Several candidate autism susceptibility genes were hypermethylated (P <0.05) in the HMFA, including Shank3, Cacana1g, Gtf2i, Rapgef4, and Nbea in male offspring and Ext1, Ube3a, Erbb4, Grip1, Grm8, Reeln, Shank3, and Rbfox1 in female offspring." (PMID 24484737, 2014). "For example, haploinsufficiency of Shank3, CMIP, FOXP2 and Tsc2 has already been linked to the etiology and phenotypic characteristics of autism." (PMID 23451085, 2013). "A recent study also identified a number of SNVs in the TSC1, TSC2, and SHANK3 genes in simplex autism cases (although the frequency of SNVs in these genes in controls was not reported)." (PMID 22558107, 2012). "Although no cases of mutations in SHANK1 have yet been identified in individuals with autism, SHANK1 is a member of the SHANK gene family, in which mutations in SHANK2 and SHANK3 have been detected in several autistic individuals." (PMID 21695253, 2011). "Candidate genes for autism include the SHANK gene family, as mutations in SHANK2 and SHANK3 have been detected in several autistic individuals." (PMID 21695253, 2011). "Recently, abnormalities at the synapse are supposed to be important for the etiology of autism.SHANK3 (SH3 and multiple ankyrin repeat domains protein) gene encodes a master synaptic scaffolding protein at postsynaptic density (PSD) of excitatory synapse." (PMID 19566951, 2009). "Rare mutations and copy number variation (CNV) evidence suggested SHANK3 as a strong candidate gene for the pathogenesis of autism." (PMID 19566951, 2009). "Here, we applied graph theory on the microscopic scale, using miniscope-based calcium imaging from the freely behaving wild type (WT) and Shank3 fx mice (a mouse model of autism), and compared functional connections among individual neurons in the prefrontal microcircuits during social behavior." (PMID 41674830, 2026). "PM2.5 may inhibit SHANK3 gene expression by inducing the hypermethylation of SHANK3 in rat brain tissues, which inhibits the SHANK3 signaling pathway and reduces synapses, thus triggering the autism phenotype." (PMID 39997934, 2025). "Shank gene variants are implicated in ~1% of people with autism, and mice lacking Shank3 exhibit autism-like behaviours." (PMID 40873709, 2025).
autism (continued). "Regarding genetic biomarkers diagnosis, autism-related genes such as SHANK3, NRXN1, and CNTNAP2 exhibit significant complexity and variability, with mutations appearing as single nucleotide polymorphisms (SNPs), small insertions or deletions (Indels), and copy number variations (CNVs)." (PMID 39734494, 2024). "Although the effects of 7-NI on social avoidance induced by ISD have not been studied previously, this compound has been shown to reverse the reduction in social interaction observed in Shank3 mutant mice, a mouse model of autism, when administered at 80 mg/kg 7 days before SIT." (PMID 39338365, 2024). "Therefore, in this study, we aimed to investigate the involvement of Trx1 in the Shank3 KO mouse model of autism." (PMID 39347996, 2024). "Accordingly, Kang Li and colleagues discovered that exposure to fine particles could result in an autism phenotype in early postnatal rats, which may be a result of the SHANK3 methylation level and the SHANK3 signaling pathway." (PMID 39199432, 2024). "Similarly, the dynamic interplay between multiple autism-related genes (e.g., SHANK3, PTEN) and their joint regulation of brain development and behavior over time has yet to be thoroughly investigated." (PMID 39734494, 2024). "Comorbid biomarkers may blur diagnostic boundaries, whereas autism-specific biomarkers—such as mutations in SHANK3, NRXN1, and CHD8—are directly tied to autism, but may also be found in other conditions like intellectual disabilities and ADHD." (PMID 39734494, 2024). "Thus, the p38α signaling is a potential target for developing drugs for treating autism, especially for the Shank3-related subset population." (PMID 38570876, 2024). "Understanding the neuronal and molecular mechanisms of Shank3-related autism could help in the treatment of some subset of autism." (PMID 38570876, 2024). "Moreover, we described binding of ADNP to proteins involved in autophagy (LC3), autism pathways (EIF4E/SHANK3), chromatin remodeling (BRG1/HP1/CDH4), and epigenetic modifying genes (SIRT1/HDAC2/YY1), all impacting the physiological status of the cell." (PMID 36945042, 2023). "Indeed, multiple studies in hiPSC-neurons and rodent models of autism have shown a hyperexcitability phenotype, strongly implicating Shank3 in E/I imbalance." (PMID 37441676, 2023). "Moreover, we also identified the downregulation of TMEM74 in the PL of Shank3 knockout mice, implying that the Tmem74 deficit in PL guides autism-like behaviors." (PMID 36690791, 2023). "In contrast, for 134 autism-associated genes, including ASH1L, ANK2 and SHANK3, we could identify at least one carrier of an S-LoF among the undiagnosed individuals, suggesting lower effect sizes on autism diagnosis." (PMID 37365347, 2023). "Indeed, the PV+ INs in V1 are hypoactive in many animal models with genetic mutations associated with autism (FRAX, RTT, SHANK3)." (PMID 36780507, 2023). "However, research on SHANK3 has mainly focused on the occurrence of autism, with little mention of the liver." (PMID 35646080, 2022).